PRL (prolactin)
Diseases named in the same sentence as PRL in open-access papers (continued):
Sharing a sentence is not in itself a finding about the gene and the disease.
hypogonadotropic hypogonadism (38 papers, 2010 to 2026). Abnormal ovarian or testicular function due to insufficient hormonal stimulation from the hypothalamic-pituitary axis. "Low estradiol levels in the presence of low-normal gonadotropins, low T4 in the presence of low-normal TSH, low PRL levels indicate central hypogonadism, central hypothyroidism and PRL deficiency respectively." (PMID 39863703, 2025). "The central hypogonadism in these patients can be due to autonomous secretion of prolactin or mass effect from the tumor resulting in elevated prolactin levels from stalk effect, which was the likely cause of elevated prolactin in our patient." (PMID 38642582, 2024). "In the absence of clinically suspected hypothalamic-pituitary disease, measurement of serum prolactin is the only diagnostic test that is routinely recommended for evaluation of causes of secondary hypogonadism of men ≥50 years." (PMID 36995891, 2023). "The finding of small testes in association with low FSH and testosterone suggests hypogonadotropic hypogonadism, and the patient's LH and prolactin levels should be evaluated as well." (PMID 22190920, 2012). "Mild TSH or PRL elevation and central hypogonadism were also observed in 9.3%, 4.6%, and 9.3% of the patients, respectively." (PMID 41596479, 2026). "Elevated prolactin can lead to decreased gonadal steroid levels and hypogonadotropic hypogonadism by suppressing pituitary hormone and follicle-stimulating hormone release, potentially resulting in various ADEs in both genders." (PMID 39833706, 2025). "Central hypogonadism, as a frequent complication of PitNETs, develops either due to tumour compression, the inhibitory effect of prolactin on gonadotropin releasing hormone (in lactotroph PitNETs), or as a complication of pituitary surgery or radiation." (PMID 40364143, 2025). "Initial neurologic examination was unremarkable, and her biochemical evaluation revealed secondary adrenal insufficiency, central hypogonadism, low serum free thyroxine, and mildly elevated serum prolactin, consistent with stalk effect." (PMID 37908996, 2023). "At diagnosis, the median PRL was 6305 μg/L (range 1450-253 000), the median tumor diameter was 47 mm (range 40-85), 84% of the patients had hypogonadotropic hypogonadism, and 71% visual field defects." (PMID 37403202, 2023). "Serotoninergic activity in turn interferes with dopaminergic signal in the mesolimbic system and can also lead to an increase of prolactin levels with subsequent hypogonadotropic hypogonadism." (PMID 37635965, 2023). "He had mildly elevated serum prolactin with hypogonadotropic hypogonadism as evidenced by low serum testosterone with luteinizing hormone and follicle-stimulating hormone in the normal range." (PMID 29568783, 2018). "Autoantibodies against gonadotropic cells were mainly found in patients affected by cryptorchidism and hypogonadotropic hypogonadism while those against prolactin cells were found in different kinds of patients, the majority without pituitary abnormalities." (PMID 29099758, 2017). "Postoperative pituitary function evaluation revealed hypogonadotropic hypogonadism and normal prolactin concentrations (prolactin: 11.8 and 10.9 ng/ml)." (PMID 22011738, 2011). "She had hypogonadotropic hypogonadism with a PRL level of 3.3 ng/ml." (PMID 39863703, 2025). "Of note, if prolactin is not elevated, a pituitary lesion has to be relatively large to cause hypogonadotropic hypogonadism, and therefore sellar computed tomography (CT) has sufficient sensitivity." (PMID 36995891, 2023). "Measurement of prolactin level is recommended in all patients with hypogonadotropic hypogonadism." (PMID 35407442, 2022). "Three patients presented gonadotropic deficiency (18.8%), all were male and did not have simultaneous elevation of prolactin." (PMID 33066179, 2020).
hypogonadotropic hypogonadism (continued). "Here we report a patient with a giant prolactinoma presented with central hypogonadism, suppressed adrenal and thyroid function, supra sellar extension, visual field impairment and high prolactin level.The patient was treated with cabergoline, levothyroxin and prednisolone." (PMID 23497585, 2013). "A comprehensive endocrine evaluation revealed secondary adrenal insufficiency, central hypothyroidism, and hypogonadotropic hypogonadism, as evidenced by low levels of ACTH, cortisol, TSH, free T4, FSH, LH, and prolactin." (PMID 41116860, 2025). "In addition, discrepancies remain on the utility of evaluating related hormones in such cases, e.g. prolactin in OAT and hypogonadotropic hypogonadism; as well as FSH and TT in oligozoospermia/OAT." (PMID 39776560, 2025). "In the presence of hypogonadotropic hypogonadism, it is recommended to carry out a pituitary MRI with a contrast agent (unless contraindicated), and to check the remaining hormonal axes with morning cortisol and ACTH, TSH, FT4, prolactin, and IGF-1 assays." (PMID 35407442, 2022). "The hypogonadotrophic hypogonadism induced by high PRL was mainly manifested by low LH, and in this situation, normal levels of FSH and estradiol do not always induce follicle recruitment and development without abnormalities in the ovary ultrasound." (PMID 36556282, 2022). "FSH, LH and prolactin are reduced in obese male GNB3-T/+ mice at 20 weeks, which could indicate hypogonadotropic hypogonadism." (PMID 29206867, 2017). "No such correlation was found suggesting that the hypogonadotropic hypogonadism in acute TBI is not due to an inhibitory effect of elevated prolactin." (PMID 23601250, 2013). "In secondary hypogonadism, prolactin levels should be obtained to rule out prolactinoma and screening for hemochromatosis should be considered." (PMID 20518947, 2010).
ovarian carcinoma (38 papers, 2007 to 2025). A malignant neoplasm originating from the surface ovarian epithelium. "GDH activity has been associated with mTORC1 activity in ovarian cancer cells, and prolactin induces the ODC expression, via mTOR signaling, in mink uterine epithelial cells; however, a relationship between GAD and mTOR signaling has not been reported." (PMID 33542926, 2021). "The calculated formula with the combination of CA125, HE4, OPN, leptin and prolactin plasma levels surpasses each single marker in its diagnostic value to discriminate between benign and malignant ovarian tumors." (PMID 34530759, 2021). "Elevation of serum prolactin, on the other hand, had also been observed in other malignancies and explored for their potential as diagnostic biomarkers, such as in lung and ovarian cancers." (PMID 23874805, 2013). "Moreover, in hepatocellular carcinoma, colorectal cancer, ovarian cancer and endometrial cancer prolactin signaling has also been implicated." (PMID 31795960, 2019). "There is some evidence that lower levels of leptin and higher levels of prolactin might be associated with increased risk of ovarian cancer." (PMID 29244844, 2017). "However, few studies have linked elevated prolactin (PRL) levels to ovarian cancer (OC)." (PMID 39928792, 2025). "In brief, the use of a PRL antagonist peptide, G129R, was shown to block the PRL : PRLR signaling axis in ovarian cancer mouse models." (PMID 36714582, 2022). "In a recent report, it has been shown that G129R-hPRL blocks the activity of PRL-PRLR signaling in ovarian cancer." (PMID 36714582, 2022). "Prolactin has been demonstrated to be elevated in serum samples of patients with ovarian cancer compared to healthy individuals and thus a biomarker of interest for the early detection of ovarian cancer." (PMID 33477343, 2021). "A study showed that ovarian carcinoma cells incubated with cisplatin reduced apoptosis when they were treated with PRL." (PMID 34745013, 2021). "A study developed in ovarian cancer (OC) cells showed that apoptosis of cells expressing PRLR was diminished after pretreatment with PRL." (PMID 34745013, 2021). "The expression of PRL and its receptor in ovarian cancer cells suggests a possible PRL loop to support growth in an autocrine manner." (PMID 34745013, 2021). "The serum profiling of both ovarian cancer individuals as well as SARS-CoV-2 patients reported an elevated level of prolactin (PRL)." (PMID 33632295, 2021). "This study investigates effects of prolactin (PRL) on ovarian cancer cells, analyzes PRL receptors (PRLR) in tissue micro arrays and relates PRLR expression to survival of ovarian cancer." (PMID 34358244, 2021). "In this study we determine the value of combining macrophage migration inhibitory factor (MIF), osteopontin (OPN), and prolactin (PROL) with CA-125 in the detection of ovarian cancer serum samples from healthy controls." (PMID 33477343, 2021). "With a logistical regression model a formula including CA125, HE4, OPN, leptin and prolactin was developed to predict malignant ovarian tumors." (PMID 34530759, 2021). "Trial on five plasma biomarkers (CA125, HE4, OPN, leptin, prolactin) and their possible role in differentiating benign from malignant ovarian tumors." (PMID 34530759, 2021). "The pooled PRL of 2.897 indicated that the probability to be ovarian cancer was 2.897-fold increased with a positive miRNA result." (PMID 32025275, 2020). "In the present study, we found evidence that HCMV infection can enhance the expression of PRLR and induce the production of PRL in ovarian cancer cells." (PMID 32121009, 2020). "Increasing evidence suggests that signaling through the prolactin/prolactin receptor axis is important for stimulation the growth of many cancers including glioblastoma multiforme, breast and ovarian carcinoma." (PMID 31063493, 2019).
ovarian carcinoma (continued). "By creating a p21 mRNA 3′UTR-luciferase mRNA construct, we demonstrated degradation of the construct in response to prolactin in human breast, prostate and ovarian cancer cell lines." (PMID 28422740, 2017). "To date we are aware of only one study that evaluated similar blood sampling conditions in relation to the concentration of established tumor markers (CA 125, prolactin) in ovarian cancer." (PMID 26236175, 2015). "Patients with high-level expression of both BRCA2 and PRL in their ovarian cancers have a worse prognosis than those with high expression of BRCA2 or PRL alone in their ovarian cancers (with a HR of 1.43 versus a HR of 1.38 or 1.25 respectively)." (PMID 25344116, 2014). "We demonstrate these effects by evaluating conditions of blood collection in one established and two novel ovarian cancer serum markers: CA 125, Prolactin, and Macrophage Migration Inhibitory Factor (MIF)." (PMID 18060075, 2007). "Prolactin has been identified as a candidate early detection marker for ovarian cancer with reports of impressively high sensitivity (>90%) and specificity (>98%)." (PMID 18060075, 2007). "Interestingly, prolactin expression seems to contribute to chemoresistance in breast and ovarian cancers." (PMID 36291915, 2022). "The role of PRL in cervical and ovarian cancer has been less investigated; however, the evidence suggests that this hormone could be strongly involved in promoting carcinogenesis through different mechanisms." (PMID 34745013, 2021). "We report the development of a blood test measuring four proteins (macrophage migration inhibitory factor, osteopontin, prolactin and cancer antigen 125), which can distinguish ovarian cancer samples, even early-stage disease, from healthy samples in the population tested." (PMID 33477343, 2021). "One of the potential biomarkers for ovarian cancer patients is high serum level of prolactin (PRL), which is a growth factor that may promote tumor cell growth." (PMID 32121009, 2020). "PRL mRNA was found expressed in human ovarian and endometrial tumor samples, and PRL administration was able to stimulate tumor proliferation in five different human endometrial and ovarian carcinoma cell lines." (PMID 33162942, 2020). "A concept similar to ours was applied in ovarian cancer, with results showing that a combination of four serologic markers (leptin, prolactin, osteopontin, and insulin-like growth factor-II) had greater sensitivity and specificity for ovarian cancer than any of these markers alone." (PMID 25188229, 2014). "We therefore hypothesized that HCMV may affect the PRL/PRLR axis in ovarian cancer." (PMID 32121009, 2020). "For instance, Prolactin, discovered in a clinical setting as a biomarker for ovarian cancer, failed in a screening setting later and turned out to be sensitive to the way samples were collected (at the day of a planned surgery or in the days before) and might just be a symptom of stress." (PMID 28270869, 2017). "In this study, HCMV’s effects on PRL and PRLR expression were assessed in infected ovarian cancer cells (SKOV3) by PCR and Western blot techniques." (PMID 32121009, 2020). "Uninfected and HCMV-infected ovarian cancer cells (SKOV3 cells) were sampled at 1, 3, and 5 dpi for detection of PRL transcripts." (PMID 32121009, 2020). "HCMV induces high levels of PRL and PRLR transcripts and proteins in HCMV-infected ovarian cancer cells." (PMID 32121009, 2020). "In conclusion, PRL and PRLR were induced to high levels in HCMV-infected ovarian cancer cells and PRLR expression was extensively detected in HCMV-infected ovarian tissue specimens." (PMID 32121009, 2020). "The final results show that the logistic regression gives high performance for both tasks, and HE4-ELISA, PDGF-AA, Prolactin, TTR is the best biomarker combination for detecting ovarian cancer." (PMID 30396341, 2018). "Highly induced PRL and PRLR by HCMV infection may be of relevance for the oncomodulatory role of HCMV in ovarian cancer." (PMID 32322296, 2020).
ovarian carcinoma (continued). "As a comparison, the levels of Prolactin did not vary between ovarian cancer stages but had clearly separated distributions in sedated and awake samples." (PMID 32867270, 2020). "Another study by Thorpe and colleagues investigated three protein biomarkers (Mucin-16, also known as CA-125), Prolactin (PRL) and Macrophage Migration Inhibitory Factor (MIF) in healthy women and women undergoing gynaecologic surgery in relation to ovarian cancer." (PMID 32867270, 2020). "Highly induced PRL and PRLR by HCMV infection may be of relevance for the oncomodulatory role of this virus in ovarian cancer." (PMID 32121009, 2020). "The combination of the mentioned six biomarkers (MIF, OPN, CA125, IGF II, leptin and prolactin) has been shown to improve differentiation between disease free and ovarian cancer patients compared to CA125 alone in patients without a family history of OC." (PMID 29244844, 2017). "Interestingly, Cdx2 and E47, known to be upregulated in ovarian carcinoma or PCOS ovaries, were repressed in the ovary at 120 min by PRL/PRL-RS signaling." (PMID 19703295, 2009). "Our data indicate a previously not recognized role for HCMV to regulate the PRL/PRLR system that may be of significance for the oncomodulatory role of HCMV in ovarian cancer." (PMID 32121009, 2020). "For prolactin, the reverse was true suggesting that prolactin levels are affected by the conditions of surgery and may not be a marker of ovarian cancer." (PMID 18060075, 2007). "Prolactin levels were not different between case and control groups after accounting for the conditions of sample collection, suggesting that sample ascertainment could explain some or all of the previously reported results about its potential as a biomarker for ovarian cancer." (PMID 18060075, 2007).
atherosclerosis (37 papers, 2011 to 2025). A disease characterized by the build-up of fatty material and calcium deposition in the arterial wall resulting in partial or complete occlusion of the arterial lumen. "(2011) investigated the relationship between prolactin levels and atherosclerosis risk factors of soluble CD40 ligand (sCD40L) and high‐sensitivity C‐reactive protein (hs‐CRP) in migraineurs between attacks." (PMID 37190874, 2023). "High levels of this hormone in patients with untreated prolactinoma were have been found to cause endothelial dysfunction and subclinical atherosclerosis, the advancement of which was dependent on the degree of prolactin hypersecretion." (PMID 37242186, 2023). "Prolactin has been associated with incident hypertension in post-menopausal women and accelerated preclinical atherosclerosis." (PMID 24219620, 2013). "In the present study, we aimed to investigate the relationship between prolactin levels and subclinical atherosclerosis risk factors such as soluble CD40 ligand (sCD40L) and high-sensitivity CRP (hsCRP) in migraine patients during interictal period." (PMID 21331754, 2011). "The enrichment of “Prolactin signaling” and “fluid shear stress and atherosclerosis” suggests broader physiological significance." (PMID 41153361, 2025). "The KEGG analysis identified 21 signaling pathways, including lipid and atherosclerosis, prolactin signaling pathway, IL-17 signaling pathway, HIF-1 signaling pathway, JAK-STAT signaling pathway, PI3K-Akt signaling pathway, among others." (PMID 38904003, 2024). "A total of 207 Kyoto Encyclopedia of Genes and Genomes signaling pathways were obtained, including the lipid and atherosclerosis pathway, the endocrine resistance pathway, the prolactin signaling pathway, and the IL-17 signaling pathway." (PMID 36401463, 2022). "Four significantly different pathways, VEGF signaling pathway, prolactin signaling pathway, renin-angiotensin system, and fluid shear stress and atherosclerosis, included 49 DEPs that were chosen for further study." (PMID 36003411, 2022). "Many pathways, including lipid and atherosclerosis, endocrine resistance pathway, prolactin signaling pathway, IL-17 signaling pathway, and others were involved in the mechanism of RPA in treating RLS." (PMID 36401463, 2022). "The KEGG enrichment results showed that the possible pathways involved in the treatment process included lipid and atherosclerosis, endocrine resistance, prolactin signaling pathway, and IL-17 signaling pathway." (PMID 36401463, 2022). "Recently, a relationship was found between prolactin levels, blood pressure and arterial stiffness, and prolactin was accused of accelerated atherosclerosis in women with early menopause." (PMID 21331754, 2011). "Notably, pathways such as PI3K-Akt, MAPK, insulin, prolactin, ErB, apelin and lipid and atherosclerosis signaling are involved in glucose metabolism, protein synthesis, and energy metabolism." (PMID 41282288, 2025). "KEGG pathway enrichment highlighted endocrine resistance, fluid shear stress and atherosclerosis, chemical carcinogenesis—reactive oxygen species, proteoglycans in cancer, relaxin/prolactin signaling, focal adhesion, and diabetic cardiomyopathy—pathways that converge on PI3K/AKT nodes." (PMID 41156454, 2025). "The top 10 pathways were morphine addiction, cell cycle, thyroid hormone signaling pathway, neuroactive ligand–receptor interaction, prolactin signaling pathway, viral carcinogenesis, Alzheimer disease, chronic myeloid leukemia, lipid and atherosclerosis, and retrograde endocannabinoid signaling." (PMID 39742014, 2024). "In vitro studies have also indicated that prolactin plays a role in the development of endothelial dysfunction in atherosclerosis through its ability to modulate the inflammatory response, stimulate vascular smooth muscle cell proliferation, and regulate mononuclear cell adhesion to the endothelium." (PMID 37174317, 2023).